CDKN2A (cyclin dependent kinase inhibitor 2A)
Diseases named in the same sentence as CDKN2A in open-access papers (continued):
Sharing a sentence is not in itself a finding about the gene and the disease.
glioma (continued). "The WHO CNS5 classification underscores the centrality of molecular markers in glioma diagnosis and prognosis, including IDH mutation, 1p/19q co-deletion, and CDKN2A/B homozygous deletion." (PMID 40507765, 2025). "According to the previous series, the possibility of finding a CDKN2A/B homozygous deletion is less than 10% in IDH-mutant gliomas." (PMID 41341389, 2025). "Nevertheless, to the best of our knowledge, this is the first study to investigate the relationship between MET- or FDG-PET and alterations in driver genes, including EGFR, PTEN, NF1, and CDKN2A/B in gliomas." (PMID 40786409, 2025). "The deletion of CDKN2A/B has been demonstrated to expedite glioma tumor progression more rapidly than other alterations in the cell cycle pathway." (PMID 40264576, 2025). "Pleomorphic xanthoastrocytoma (PXA) is a rare, localized glioma characterized by frequent BRAF V600E mutations and CDKN2A/B deletions." (PMID 40231261, 2025). "Meanwhile, upregulation of Cdkn2a gene expression was reported for a number of glioma cell lines such as T98G, U87-MG, and SW1783 MG." (PMID 41009560, 2025). "Therefore, combinatorial treatments compensating also for loss of function mutations (e.g. CDK4/6 inhibition for homozygous CDKN2A/B deletion) and targeted elimination of glioma stem cells before clonal evolution occur, could increase treatment success in these tumor entities." (PMID 41331048, 2025). "Background/Objectives: Astrocytoma IDH-mutant CNS WHO grade 4 is a malignant tumor of the central nervous system characterized by tumor necrosis, microvascular proliferation, and/or homozygous CDKN2A/B deletion." (PMID 41562896, 2025). "With the fifth edition of the WHO classification of Tumours of the Central Nervous System (CNS), presence of homozygous CDKN2A/B deletions mandates a CNS WHO grade 4 designation of IDH-mutant astrocytoma independent of histological features." (PMID 39899075, 2025). "Histopathology showed glial tumors with either low-grade or high-grade characteristics, while molecular characterization found an additional homozygous CDKN2A/B deletion in two cases." (PMID 38902810, 2024). "For example, the complete codeletion of 1p/19q indicates oligodendrogliomas, the partial or total absence of this codeletion indicates astrocytoma, and the presence of a homozygous deletion in CDKN2A/B corresponds to the highest-grade glioma." (PMID 38736685, 2024). "According to the 2021 WHO classification, all IDH mutated diffuse, astrocytic, grade 2 and 3 gliomas should be tested for CDKN2A/B homozygous deletion, since the presence of this marker would assign a grade 4 glioma." (PMID 37776502, 2024). "In summary, we have identified the MAPK pathway as a tumor cell intrinsic rebound driving mechanism in pediatric glioma cells with BRAFV600E mutation and CDKN2A/Bdel." (PMID 38630384, 2024). "GLIMMERS is an open-source tool to facilitate assessment of CNV markers related to classification and grading of gliomas, including 1p/19q, CDKN2A/B, EGFR, and +7/−10." (PMID 38736685, 2024). "Amongst IDH-mutant gliomas, the homozygous deletion of CDKN2A/B has been shown to be an important marker for adverse clinical outcomes and this has been reflected in the updated grading scheme of the IDH-mutant astrocytoma." (PMID 38893099, 2024).
glioma (continued). "Further molecular interrogation of the tumor revealed a neurotrophic tyrosine receptor kinase (NTRK) gene fusion and CDKN2A deletion more commonly seen in infantile high-grade gliomas." (PMID 39108689, 2024). "In IDH-mut gliomas the survival effect of intact CDKN2A/B resembles that of the survival benefit from post-radiation chemotherapy in low grade IDH-mut gliomas (HR = 0.38) in the RTOG9802 trial." (PMID 39593128, 2024). "Homozygous deletions of CDKN2A/B emerge as potent biomarkers in gliomas, leading to uncontrolled cell cycle activity and increased cell proliferation." (PMID 39593128, 2024). "In previous studies about CDKN2A status in IDH-mutant gliomas, 11–18% of astrocytoma, IDH-mutant showed CDKN2A-HD." (PMID 39117984, 2024). "The primary aim of the present study was to investigate the role of CDKN2A/B deletion as a poor prognostic factor for CNS WHO grade 4 gliomas." (PMID 39457569, 2024). "In this TCGA cohort of lower-grade gliomas, grade 4 tumours were called as such based on presence of CDKN2A/B deletion." (PMID 38877600, 2024). "In conclusion, the present meta-analysis is the first investigation using reconstructed IPD to analyze the impact of homozygous CDKN2A/B deletions on OS in 714 IDH-wt or IDH-mut gliomas." (PMID 39593128, 2024). "Essentially, the presence of CDKN2A/B deletion marks a critical decline in prognosis for IDH-mut gliomas." (PMID 39593128, 2024). "Median survival of patients with IDH-wt glioma and homozygous CDKN2A/B deletion was 13.0 months (95%-CI 11.2–14.8)." (PMID 39593128, 2024). "Median OS of patients with IDH-wt gliomas and homozygous CDKN2A/B deletion was 13.0 months compared to 18.0 months with non-deleted CDKN2A/B (p = 0.014, Log-Rank)." (PMID 39593128, 2024). "The survival effect of intact CDKN2A/B in IDH-wt gliomas quantitatively reaches that of the survival benefit of the addition of temozolomide to radiotherapy in the “Stupp” trial in GBM (HR = 0.63)." (PMID 39593128, 2024). "We discovered that on average, 23.8% of gliomas have some form of CDKN2A/B deletion, either heterozygous or homozygous." (PMID 39593128, 2024). "CDKN2A deletion has a stronger predictive power for prognosis than IDH mutation, which is a well-known traditional player in the prognosis of patients with glioma." (PMID 39457569, 2024). "With the recent 2021 update of the WHO Classification of Central Nervous System Tumors, homozygous deletions of CDKN2A/B are sufficient to classify meningiomas as CNS WHO grade 3 tumors regardless of histological grading." (PMID 39358739, 2024). "Age, FGFR2, IDH1, CDK4, CDK6, KIT, and CDKN2A were considered vital indicators related to the prognosis and OS time of glioma." (PMID 37273702, 2023). "This study is the first to propose the use of noninvasive imaging to build radiomic models for CDKN2A/B homozygosity deletion in gliomas." (PMID 37190513, 2023). "CDKN2A homozygous deletion was a robust adverse prognosis factor in diffuse malignant IDH-mutant gliomas." (PMID 37273702, 2023). "Two BRAF-rearranged gliomas had TERT promoter mutations and five had loss of CDKN2A/B, all of which were grade 4." (PMID 36854806, 2023). "Some alterations such as CDKN2A/B loss, PTEN, EGFR, NF1, and TERT promoter mutations have been shown to be associated with very poor clinical outcomes in patients with BRAF-altered gliomas." (PMID 37920169, 2023). "A retrospective study was conducted in 173 gliomas of all types, using p16 IHC and CDKN2A fluorescent in situ hybridization." (PMID 36900302, 2023).
glioma (continued). "Based on their prognostic relevance in glioma samples, the seven variables age, FGFR2, IDH1, CDK4, CDK6, KIT, and CDKN2A were selected for the construction of the WHO5 risk signature." (PMID 37273702, 2023). "Our study innovatively used radiomics to determine the association between MRI features and CDKN2A/B homozygous deletion in gliomas, constructing a CDKN2A/B predictive model." (PMID 37190513, 2023). "We also provided a historical review of the changing impact of CDKN2A/B alterations as glioma classification has evolved over time." (PMID 37504251, 2023). "The homozygous CDKN2A deletion is a strongly unfavorable prognostic factor for survival outcomes of patients with IDH-MT or WT glioma." (PMID 37908227, 2023). "Timeline of the evidence landscape for CDKN2A/deletions in gliomas, highlighting key findings from the respective studies." (PMID 37504251, 2023). "The results showed that patients in different groups defined by age, FGFR2, IDH1, CDK4, CDK6, KIT, and CDKN2A had significantly different OS in all glioma grades." (PMID 37273702, 2023). "Through this study, we aimed to construct a template for CDKN2A/B homozygous deletion study models for gliomas, contributing to the development of clinical treatment plans." (PMID 37190513, 2023). "Given the recency of this change, the literature on correlating imaging features with CDKN2A/B status in gliomas is sparse." (PMID 37316586, 2023). "Using single-strand conformation polymorphism (SSCP) and quantitative polymerase chain reaction (qPCR), they showed an increased incidence of CDKN2A/B HD in high-grade gliomas (44%, n = 12/27) compared to low-grade gliomas (10%, n = 1/10)." (PMID 37504251, 2023). "As interest in CDKN2A deletions increased, there was further focus on glioma subtypes, including oligodendrogliomas." (PMID 37504251, 2023). "Zhang and colleagues mapped the co-deletion of genes adjacent to CDKN2A in 14 cell lines, including gliomas." (PMID 37504251, 2023). "Patients with IDH-mutant gliomas that present with either homozygous or heterozygous CDKN2A deletion have decreased progression-free and overall survival." (PMID 38135704, 2023). "Our results showed that the combined chromosome 7 gain/10 loss and TERT promoter mutation associated with high INTS9 in the IDH wildtype astrocytoma during the CDKN2A/CDKN2B homozygous deletion in the IDH mutant glioma." (PMID 37537630, 2023). "In an experimental model, PDGFA enhanced the growth of IDH1R132H mutant immortal Cdkn2a, Atrx, and Pten deficient astrocytes and PDGFA cooperated with IDH1R132H and loss of Cdkn2a, Atrx, and Pten to promote glioma formation in vivo." (PMID 38012788, 2023). "In the 2021 WHO classification of CNS tumors, CDKN2A/B homozygous deletion became one of the bases of glioma classification, which emphasized the importance of CDKN2A in the development of glioma." (PMID 36936439, 2023). "The 2021 WHO classification identified novel molecular subtypes, including CDKN2A homozygous deletion status in gliomas." (PMID 38135704, 2023). "Currently, molecular markers for adult glioma classification and prognosis include IDH1/2 mutations, homozygous deletion of CDKN2A and/or CDKN2B, EGFR amplification, and TERT promoter mutation." (PMID 37214395, 2023). "The findings indicate that p16 immunohistochemistry is a reliable surrogate marker of CDKN2A homozygous deletion in gliomas, with recommended p16 cutoff scores of ≤ 5% for confirming and > 20% for excluding biallelic CDKN2A loss." (PMID 37138345, 2023). "This study aimed to investigate the association between conventional MRI and CDKN2A/B, and to establish a pre-surgery model of CDKN2A/B homozygous deletion in patients with gliomas." (PMID 37190513, 2023). "Primary genetic markers such as IDH mutations, CDKN2A deletions, 1p/19q‐codeletions, H3F3A alterations, MGMT promoter methylation status and EGFR amplification are used in the glioma classification system." (PMID 36999945, 2023).
glioma (continued). "CDKN2A is the second most impaired tumor suppressor gene in cancers, including gliomas, and its inactivation promotes the G1-S phase transition." (PMID 36900302, 2023). "It establishes p16 as a reliable, highly sensitive surrogate marker for inference of CDKN2A homozygous deletion in gliomas, with a recommended p16 expression score of ≤ 5% for confirming and > 20% for excluding CDKN2A homozygous loss." (PMID 37138345, 2023). "Namely, the role of secondary mutations in epigenetically driven glioma has only been superficially defined, with an unclear role of key oncogenic driver genes such as EGFR, PTEN, RB1, NF1, TERT, and CDKN2A on modulating the tumor microenvironment." (PMID 37706202, 2023). "Our findings therefore seem to support the inclusion of CDKN2A status as a grade-defining molecular finding for the grading of gliomas, as acknowledged in this new classification of gliomas by the WHO." (PMID 36968138, 2023). "CDKN2A/B homozygosity deletion serves as a prognostic predictor for gliomas, predicting poorer OS, and providing treatment guidance." (PMID 37190513, 2023). "Another study using the RCAS/TVA system demonstrated that glioma-genesis in the context of mutant IDH1 with shp53 and/or Cdkn2a loss, was only facilitated when combined with PDGFa." (PMID 38012788, 2023). "The deletions of the CDKN2A/B gene and their impact on tumor progression, along with clinical outcomes, have also been demonstrated in other malignant CNS tumors, such as gliomas." (PMID 38017560, 2023). "Cyclin-Dependent Kinase Inhibitor 2A/B (CDKN2A/B) homozygous deletion was a significant prognostic factor for gliomas and affected the treatment strategy." (PMID 37190513, 2023). "Of the 17 gliomas in our molecular high-grade group, 82% had either CDKN2A inactivation (n = 13) or CDK4 amplification (n = 1)." (PMID 35945463, 2022). "The third subgroup corresponds to WHO grade 4 gliomas when at least one of the following features is identified: microvascular proliferation, necrosis, or CDKN2A/B homozygous deletion." (PMID 35756624, 2022). "NT-2 gliomas were also enriched with CDKN2A/B-deleted gliomas (105/188 samples, 55.9% and 103/188 samples, 54.8%, respectively)." (PMID 35455749, 2022). "In this study, FGFR1 SVs in glioma were found to be co-occurring with H3-3A and mutually exclusive with CDKN2A/2B." (PMID 36462464, 2022). "Another molecular alteration suggested as driver of inferior survival in IDH-mutant gliomas and frequently present in oligosarcomas are homozygous CDKN2A/B deletions." (PMID 34967922, 2022). "Genetic alterations, such as PDGFB amplification, the homozygous loss of Cyclin Dependent Kinase Inhibitor 2A (CDKN2A), and coding for p16INK4A and p14ARF, show high frequency in human glioma." (PMID 36358353, 2022). "MTAP is frequently co-deleted with CDKN2A in a wide variety of cancers such as malignant pleural mesothelioma, non-small cell lung cancer, and gliomas." (PMID 36572880, 2022). "We found that both FDX1 and CDKN2A were highly expressed in WHO 2/3 glioma tissue samples compared to normal brain tissue by immunohistochemistry." (PMID 36059638, 2022). "CDKN2A genetic alterations are found in low grade gliomas often with BRAF genetic alterations and correlate with later clinical progression." (PMID 35574540, 2022).
glioma (continued). "For example, loss of CDKN2A/B homozygosity is closely related to poor prognosis, especially in WHO grade III glioma with loss of CDKN2A/B homozygosity, where the prognosis is similar to WHO grade IV glioma." (PMID 35711921, 2022). "In gliomas, loss of MTAP expression is associated with 9p21 locus deletion and as shown based on the data in cBioPortal it is often co-deleted with CDKN2A in many cancers." (PMID 36572880, 2022). "In other words, CDKN2A/B homozygous deletion represents a tipping point that tolls the knell for the favorable outcome of IDH-mutant glioma." (PMID 35203456, 2022). "In particular, Cdkn2a+/+ mice with IDH1-mutant glioma had significantly longer median survival; however, they completely lost the survival advantage—and indeed faced a greater reduction in median survival—upon genetic deletion." (PMID 35203456, 2022). "In glioma patients, the levels of CDKN2A, FDX1, DLD, DLAT, LIAS, LIPT1, and PDHA1 were significantly associated with the OS, disease-specific survival, and progression-free interval." (PMID 36579333, 2022). "The ddPCR-based assay for CDKN2A copy number analysis was evaluated by mixing DNA from CDKN2A homozygously deleted U87-MG cells with tumor DNA from a glioma that had retained both CDKN2A copies by ddPCR analysis (copy number: 1.85 ± 0.02)." (PMID 35361262, 2022). "According to cIMPACT-NOW update 5 and the upcoming WHO classification for tumors of the central nervous system, homozygous CDKN2A/B deletions correspond to WHO CNS grade 4 in IDH-mutant astrocytomas." (PMID 34967922, 2022). "Homozygous deletion of CDKN2A can contribute to uncontrolled tumor cell proliferation, and has been reported as a poor prognostic marker in adult glioma." (PMID 33673070, 2021). "Homozygous deletion of the CDKN2A/B gene was detected in a larger proportion of the glioblastoma IDH-wildtype tumors (9/15) compared to glioma IDH-mutant tumors (9/106) (Fisher’s exact test p value < 0.001)." (PMID 33941250, 2021). "In high TNFSF13 gliomas, somatic mutation was proved to correlate with amplification of EGFR and deletion of CDKN2A; while mutation of IDH1 was more frequently observed in low TNFSF13 group." (PMID 34712225, 2021). "Based on these limitations, our findings on the prognostic role and therapeutic implications of subventricular zone involvement in glioma WHO grade 2 warrant evaluation in prospective cohorts which consider novel prognostic markers such as CDKN2A/2B deletion." (PMID 34625590, 2021). "CDKN2A homozygous deletion has been well‐analyzed in many tumors, including glioma, and frequently reported as a poor prognostic marker in patients with IDH‐mutant diffuse astrocytic glioma." (PMID 33838014, 2021). "Our results showed the possible synergy of CDKN2A and CDKN2B HDs with BRAF mutations, especially in adult glioma patients with BRAFV600E and BRAFnon-V600E." (PMID 33980169, 2021). "Conversely, later-onset gliomas were associated with the IDHwt subtype paired with EGFR or MDM4 amplification, as well as with CDKN2A, CDKN2B, or PTEN deletion (FDR <0.015)." (PMID 34788626, 2021). "Future development of novel chemotherapeutic agents targeting CDKN2A alternation would be a promising approach not only for IDH‐mutant gliomas but also for GBMs with unmethylated MGMT." (PMID 33838014, 2021). "In the present study, we tried to analyze the prognostic significance of epidermal growth factor receptor (EGFR) amplification and CDKN2A alteration on regulated genes in patients with glioma." (PMID 33959491, 2021).